RNU6-528P (RNA, U6 small nuclear 528, pseudogene)
Gene: Small nuclear RNA gene on chromosome 8 (33,338,867 to 33,338,966, forward strand). Ensembl gene ENSG00000252735.
Homologues: Orthologues: chimpanzee U6 (90% identical), dog U6 (73% identical), rabbit U6 (70% identical), rat LOC120095355 (60% identical). Paralogues in human: RNU6-356P (76% identical), RNU6-470P (76% identical), RNU6-1172P (75% identical), RNU6-1331P (75% identical), RNU6-380P (75% identical), RNU6-445P (75% identical), RNU6-593P (75% identical), RNU6-797P (75% identical), RNU6-1056P (74% identical), RNU6-1145P (74% identical), RNU6-1209P (74% identical), RNU6-1329P (74% identical), and 1285 more.